TLR4 (toll like receptor 4)
Diseases named in the same sentence as TLR4 in open-access papers (continued):
Sharing a sentence is not in itself a finding about the gene and the disease.
cardiac hypertrophy (continued). "In contrast, some molecules and compounds negatively regulate cardiac hypertrophy by suppressing TLR4/MyD88 signaling, which includes protein molecules such as MD1 and anti-HSP70 antibody and compounds such as Ang II type 1 receptor (AT1-R) antagonist and liver × receptors agonist." (PMID 37113698, 2023). "The development of cardiac hypertrophy as a result of these stresses may be the result of the interaction of multiple pathways, such as TLR4." (PMID 38140398, 2023). "Therefore, we suggest a careful examination of the etiology of cardiac hypertrophy (or failure) when evaluating TLR4 signaling as a target for possible future cardiac therapies." (PMID 38140398, 2023). "Our results speculate that the BRD4/TLR4 axis might be a promising strategy for treating cardiovascular diseases with cardiac hypertrophy, including HF." (PMID 36247184, 2022). "Therefore, a blockade of excessive TLR4 expression is a promising therapeutic strategy for cardiac hypertrophy in HF." (PMID 36247184, 2022). "TLR4 mediates Ang II-induced cardiac hypertrophy, remodeling, fibrosis, and cardiac dysfunction." (PMID 36247184, 2022). "Activation of TLR4 leads to the progression of cardiac hypertrophy and injury." (PMID 36324504, 2022). "TLR4/NF-κB is a signaling pathway that is activated during myocardial hypertrophy." (PMID 36247184, 2022). "Summary of the TLR4 signaling ligands in cardiac hypertrophy and cardiac remodeling." (PMID 33324685, 2020). "Additionally MIAT expression is upregulated in cardiomyocytes under AngII treatment, participating as an inducer of cardiac hypertrophy by activation of the PI3K/Akt/mTOR pathway via TLR4 upregulation by sponging miR-93 in cardiomyocytes." (PMID 32754048, 2020). "Additionally, Bauer and colleagues elucidated the role for HMGB1/TLR4 interaction in driving right ventricular hypertrophy, suggesting that TLR4/HMGB1 axis is involved in the development of cardiac hypertrophy." (PMID 33324685, 2020). "Functionally, TLR4 activation initiates the signaling cascade giving rise to a large repertoire of inflammatory cytokines, that reportedly regulate inflammatory responses and progression of cardiac hypertrophy." (PMID 33324685, 2020). "This section discusses TLR4's function in cardiac hypertrophy." (PMID 33324685, 2020). "TLR4 mediates Ang II-induced pathological cardiac hypertrophy and HF36." (PMID 32029708, 2020). "Collectively, these findings suggest that the TLR4/TRIF pathway is involved in cardiac hypertrophy." (PMID 33324685, 2020). "Therefore, one of the mechanisms of cardiac hypertrophy is mediated by activation of the PI3K/Akt/mTOR signaling pathway under TLR4 stimulation, which brings a detrimental effect on the heart." (PMID 33324685, 2020). "In addition, inhibition of extracellular HSP70 (one of the TLR4 ligands) binding to TLR4 was found to attenuate pressure overload-induced cardiac hypertrophy and fibrosis by modulating ERK and p38 MAPK activity, further corroborating the previous studies." (PMID 33324685, 2020). "Many studies have shown that deletion of TLR4 may protect heart from ischemia reperfusion injury, cardiac hypertrophy and other cardiac complications." (PMID 33159115, 2020). "Finally, we provide examples of some of the most promising drugs and new technologies that have the potential to attenuate TLR4-mediated inflammatory response and prevent or reverse the ominous cardiac hypertrophy outcomes." (PMID 33324685, 2020). "Therefore HSPs are important ligands that bind TLR4 and regulate production of inflammatory cytokines and the development of cardiac hypertrophy." (PMID 33324685, 2020). "B(a) P was reported to cause defect of cardiovascular development by aryl hydrocarbon receptor or up regulated of rbp4 and may results in cardiac hypertrophy by activating TLR4/MyD88 signal pathway." (PMID 30112104, 2018). "This indicates that TLR4 inhibitor could terminate the cardiac hypertrophy complications and its progression." (PMID 28690610, 2017).
cardiac hypertrophy (continued). "Overall, this indicates that TLR4 is required for angiogenesis and myocardial hypertrophy." (PMID 28765537, 2017). "We also assessed PRDX2 participation in angiogenesis and myocardial hypertrophy and whether it may be mediated by TLR4." (PMID 28765537, 2017). "Therefore, the primary objective of the present study was to find the role of TLR4 in cardiac hypertrophy and the molecular mechanism thereof." (PMID 28690610, 2017). "However, in the present study, we have analyzed the effect of TLR4 modulation, i.e., both TLR4 agonist and antagonist on isoproterenol-induced rat cardiac hypertrophy focusing more on mitochondrial dysfunction." (PMID 28690610, 2017). "Similarly, TLR4 inhibitor “Iritoran” has protective effect against cardiac hypertrophy through PI3K/Akt/mTOR axis." (PMID 28690610, 2017). "However, inhibition of TLR4 attenuated cardiac hypertrophy through reduced cardiac redox imbalance and mitochondrial dysfunction." (PMID 28690610, 2017). "This increased TLR4 activation due to DAMP released from mitochondria may lead to excessive cardiomyocyte damage in a state of cardiac hypertrophy." (PMID 28690610, 2017). "Protein and gene expression of TLR4 was significantly increased in cardiac hypertrophy." (PMID 28690610, 2017). "After the detection of elevated TLR4 transcripts after 14 days of TAC, we assumed that TLR4 expression might increase early on and accounts for prolonged inflammation in TLR2 deficient mice, thereby promoting cardiac hypertrophy development." (PMID 27109115, 2016). "The TAC induced increase of TLR4 mRNA expression might support the assumption that TLR4 signaling is a major contributor to the development of cardiac hypertrophy." (PMID 27109115, 2016). "Previous research revealed that TLR4 promotes cardiac hypertrophy in vivo." (PMID 27109115, 2016). "In conclusion, evidence is presented that cardiac TLR2 and TLR4 signaling pathways may be key in renal I/R-induced cardiac hypertrophy and electrical dysfunction through mechanisms that involve MyD88 and NF-κB." (PMID 26448184, 2015). "Knockout mice helped to determine whether TLR2 or TLR4 were key participants in I/R-induced cardiac hypertrophy." (PMID 26448184, 2015). "Contrariwise, TLR4-disruption could compensate for the detrimental effects on cardiac hypertrophy in SIRP-α knockdown hearts." (PMID 26588247, 2015). "Tlr4-/- mice are protected from extensive cardiac hypertrophy." (PMID 26588247, 2015). "TLR4 knockout mice develop less cardiac hypertrophy induced by pressure overload." (PMID 26448184, 2015). "Furthermore, we assumed that Tlr4-/- mice responding to TAC with reduced cardiac hypertrophy and inflammation are protected from a LTA or CpG-ODN induced hyperinflammatory cardiac response." (PMID 26588247, 2015). "Prevention of the I/R-induced cardiac hypertrophy in either TLR2-/- or TLR4-/- transgenic mice (5A and B) gives further support to the idea that these receptors act centrally in the signaling mechanisms of renal I/R-induced cardiac hypertrophy and inflammation." (PMID 26448184, 2015). "TLR4 has been reported to induce myocardial hypertrophy via activation of MYD88 and NF-κB pathway." (PMID 25546437, 2014). "Knockout of TLR4 has been shown to reduce pressure overload-induced cardiac hypertrophy in mice." (PMID 25546437, 2014). "Interestingly, lipopolysaccharide, a specific TLR4 agonist, leads to myocardial hypertrophy through the calcineurin signaling pathway." (PMID 22778498, 2012). "When the PI3K/Akt/mTOR pathway was inhibited, a more prominent decrease in cardiac hypertrophy, NF-κB, and IκBb was noted, providing evidence that TLR4 downstream metabolites can be affected by different TLR pathways which could be contributing to cardiac hypertrophy." (PMID 38140398, 2023). "However, determining whether the NF-κB (P65)/TLR4 signaling pathway is involved in the protective effects of TA injection on cardiac hypertrophy will require further investigation." (PMID 32499705, 2020).
cardiac hypertrophy (continued). "In the past decades, accumulating evidence has implicated TLR4-mediated inflammatory response in regulation of myocardium hypertrophic remodeling, indicating that regulation of the TLR4 signaling pathway may be an effective strategy for managing cardiac hypertrophy's pathophysiology." (PMID 33324685, 2020). "However, the application of extracellular HSP70 antagonism in mice revealed that blockade of combining HSP70 with TLR4 decreases macrophage infiltration and inflammatory cytokine expression, thereby attenuating pressure overload-induced cardiac hypertrophy and fibrosis." (PMID 33324685, 2020). "Moreover, chronic intermittent hypoxia, the most characteristic pathophysiological change of obstructive sleep apnea syndrome, has been reported to induce cardiac hypertrophy in animal models, and the beneficial cardiac effects are produced by inhibition of the TLR4/MyD88/NF-κB pathway." (PMID 33324685, 2020). "Therefore, we hypothesized that pharmacological modulation of TLR4 mitigates cardiac hypertrophy in rats, via attenuation of oxidative stress and mitochondrial dysfunction." (PMID 28690610, 2017). "Other MyD88-dependent pathways include the TLR4/MyD88/CaMK II, TLR4/MyD88/PI3K/Akt, and TLR4/MyD88/MAPK pathways, showing that TLR4/MyD88 downstream is more complicated in regulating cardiac hypertrophy." (PMID 37113698, 2023). "The TLR4/MyD88/PI3K/Akt pathway has both adverse and protective effects on cardiac hypertrophy, probably due to the different PI3K isoforms." (PMID 37113698, 2023). "TLR4 overexpression attenuated cardioprotection against Ang II by BRD4 silencing, including cardiac hypertrophy, oxidative stress, and inflammatory cytokine production." (PMID 36247184, 2022). "However, the molecular mechanisms that modulate TLR4 in cardiac hypertrophy remain unclear." (PMID 36247184, 2022). "In Ang II-induced hypertension rats, a blockade of TLR4 delayed the progression of hypertension and reduced the TNF-α and IL-1β levels and NF-κB activity in myocardial tissue, which improved cardiac hypertrophy." (PMID 36247184, 2022). "Previous studies have demonstrated upregulation of TLR4 mRNA and HMGB1 protein in cardiac hypertrophy mice following TAC." (PMID 33324685, 2020). "Another study investigated HMGB1 in H9c2 cells, and found that HMGB1 alone had no influence in cardiac hypertrophy but aggravated myocardial hypertrophy in the context of pressure/mechanical stress stimulation, which also caused a prompt upregulation of the expression of TLR4 in cardiomyocytes." (PMID 33324685, 2020). "In fact, its deficiency normalized the glucose transporter-4 (GLUT4) expression in cardiomyocytes and attenuated hypertrophic response to pressure overload, whereas TLR4 or MyD88 knockdown attenuated RBP4-induced insulin resistance and cardiac hypertrophy." (PMID 33324685, 2020). "MIAT-mediated sponging of miR-93 led to upregulation of TLR4 and activation of hypertrophic PI3K/Akt/mTOR signaling, thereby leading to AngII-induced cardiac hypertrophy." (PMID 32241300, 2020). "Consequently, the TLR4/HMGB1 axis may be a new therapeutic target for cardiac hypertrophy." (PMID 33324685, 2020). "It is worth noting that the degradation of activated TLR4 by ubiquitination was shown to attenuate pressure overload-induced cardiac hypertrophy and improve cardiac function, indicating that it may be an important approach for preventing progression of cardiac hypertrophy." (PMID 33324685, 2020). "Recent studies utilizing different models of cardiac hypertrophy revealed, that MCP-1 and monocyte/macrophage recruitment depended on TLR4 signaling." (PMID 26588247, 2015). "TLR4 inhibition within the PVN attenuated MAP, improved cardiac hypertrophy, reduced TNF-α, IL-1β, iNOS levels, and NFκB activity in SHR but not in WKY rats." (PMID 25879545, 2015).
cardiac hypertrophy (continued). "Further research is needed to fully understand the balance between the negative effects of TLR4 signaling activation on cardiac function and the positive role of TLR4 activation in inducing cardiac hypertrophy." (PMID 38140398, 2023). "In addition, inhibition of TLR4 in the PVN further decreased inflammatory cytokines and was responsible for diminished sympathoexcitation in SHRs, which led to a decrease in cardiac hypertrophy." (PMID 37034342, 2023). "In particular, enhancement of TLR4 signaling has been reported to trigger ROS production, inflammation and CD68+ macrophage infiltration, leading to cardiac hypertrophy, fibrosis and HF, whereas administration of TLR4 antagonist prevented cardiac hypertrophy and dysfunction." (PMID 36012897, 2022). "Our study showed that the mRNA and protein of TLR4 were reduced by BRD4 silencing in H9c2 cells with Ang II, and TLR4 overexpression could attenuate cardiac hypertrophy change, oxidative stress, and inflammatory cytokine production." (PMID 36247184, 2022). "TLR4/TRIF plays a role in cardiac remodeling after myocardial infection and cardiac hypertrophy." (PMID 36289897, 2022). "We further verified the expression of TLR4 signaling pathway molecules with or without DSELD in the myocardial hypertrophy model." (PMID 35046797, 2021). "RBP4-induced TLR4 expression activates the NLRP3 inflammasome in mice, which leads to the expression of inflammatory cytokines such as IL-1β, promotes insulin resistance and cardiac hypertrophy." (PMID 34638803, 2021). "Overall, these findings suggest that RBP4, through the TLR4-mediated signaling pathway, not only directly impair GLUT4 expression in cardiomyocytes but also promote expression of pro-inflammatory cytokines and cardiac hypertrophy." (PMID 33324685, 2020). "In one study, interference with TLR4 expression was found to blunt ERK1/2 and p38 MAPK phosphorylation levels in spontaneously hypertensive rats, and subsequently improved vascular inflammatory response and cardiac hypertrophy." (PMID 33324685, 2020). "The mitochondrial perturbations that were observed in hypertrophy heart was normalized after administration of TLR4 inhibitor but not with the agonist." (PMID 28690610, 2017). "We set out therefore to: (i) test the hypothesis that a unilateral renal I/R model can induce cardiac hypertrophy; and, if confirmed, (ii) assess whether TLR2 and TLR4 are involved in renal I/R-induced CH." (PMID 26448184, 2015). "It has been shown that a lack of TLR4 signaling diminishes cardiac hypertrophy following aortic banding." (PMID 26588247, 2015). "Therefore, it is speculated that Trim44 may regulate the ubiquitination level of TLR4 in myocardium, affecting the activation state of the AKT/mTOR signaling pathway and thus participating in the regulation of cardiac hypertrophy." (PMID 35855640, 2023). "Furthermore, some studies that examined the effects of TLR4 on cardiac hypertrophy did not assess dynamic cardiac function or examined it but only after a few days of aortic constriction surgery." (PMID 38140398, 2023). "Our findings suggest that TLR4 signaling may play a key role in chronic HFD-induced cardiac hypertrophy and inflammation but does not by itself modulate dynamic cardiac function." (PMID 38140398, 2023). "Besides, Ang II activates STAT3, which interacts with TLR4 and increases IL-6, and, in turn, promotes the second STAT3 activation, leading to an upregulated expression of genes for cardiac hypertrophy through the IL-6/glycoprotein 130 (gp130)/Janus-family tyrosine kinases 2 (JAK2) pathway." (PMID 37113698, 2023). "Particularly, administration of a specific TLR4 blocker, viral inhibitory peptide within the paraventricular nucleus, downregulated HMGB1 in both circulation and brain, and this was accompanied by downregulation of pro-inflammatory cytokines as well as improvement of cardiac hypertrophy." (PMID 33324685, 2020).
cardiac hypertrophy (continued). "Moreover, severe injury such as cardiac hypertrophy is displayed, which indicates the involvement of several DRGs of IL6, LUM, LRG1, PLG, with other molecules such as Alpha actinin, PDGF, Tgf beta, and TLR2 and TLR4." (PMID 32753925, 2020). "However, there was no improvement of all these parameters in TLR4 agonist (LPS)-treated hypertrophy heart." (PMID 28690610, 2017). "Furthermore, this study demonstrates for the first time that a lack of TLR4 signaling does not only reduce cardiac hypertrophy and inflammation but also protects Tlr4-/- mice from hyper-responsiveness towards subsequent virulence factor challenges." (PMID 26588247, 2015). "These contradictory results were clarified in the study by Han and colleagues who found that Ang II directly interacts with MD2 to facilitate the MD2/TLR4 complex formation, a process that is independent of LPS, it seems to explain why CD14 does not work in Ang II-induced cardiac hypertrophy." (PMID 33324685, 2020).